RNU4-13P (RNA, U4 small nuclear 13, pseudogene)
Gene: Small nuclear RNA gene on chromosome 17 (59,537,359 to 59,537,499, reverse strand). Ensembl gene ENSG00000200889.
Homologues: Orthologues: chimpanzee U4 (98% identical), macaque U4 (96% identical), dog U4 (60% identical). Paralogues in human: RNU4-67P (89% identical), RNU4-7P (89% identical), RNU4-44P (89% identical), RNU4-68P (86% identical), RNU4-23P (85% identical), RNU4-35P (85% identical), RNU4-58P (85% identical), RNU4-76P (85% identical), RNU4-31P (84% identical), RNU4-8P (84% identical), RNU4-45P (84% identical), RNU4-92P (84% identical), and 82 more.